RNU7-3P (RNA, U7 small nuclear 3 pseudogene)
Synonyms: U7.3
Gene: Small nuclear RNA gene on chromosome 6 (149,516,956 to 149,517,017, forward strand). Ensembl gene ENSG00000252244.
Homologues: Orthologues: chimpanzee U7 (98% identical), macaque U7 (95% identical). Paralogues in human: RNU7-11P (94% identical), RNU7-4P (94% identical), RNU7-25P (92% identical), RNU7-46P (92% identical), RNU7-47P (92% identical), RNU7-7P (92% identical), RNU7-1 (90% identical), RNU7-13P (90% identical), RNU7-14P (90% identical), RNU7-22P (90% identical), RNU7-28P (90% identical), RNU7-6P (90% identical), and 143 more.